SPHK2 (sphingosine kinase 2)
Diseases named in the same sentence as SPHK2 in open-access papers (continued):
Sharing a sentence is not in itself a finding about the gene and the disease.
Sepsis (5 papers, 2016 to 2024). Sepsis is defined as life-threatening organ dysfunction caused by a dysregulated host response to infection. "We therefore tested the influence of altered systemic S1P levels in circulation on VEC barrier stability and sepsis severity by inducing a systemic polymicrobial infection to wt, SphK1−/− and SphK2−/− mice." (PMID 36361636, 2022). "If systemic S1P levels were relevant for sepsis severity, SphK1−/− mice and SphK2−/− mice should demonstrate opposite outcomes post infection." (PMID 36361636, 2022). "In order to investigate the role of SphK1 and SphK2 in sepsis, we used the experimental sepsis model of polymicrobial peritoneal contamination and infection (PCI) in mice." (PMID 36361636, 2022). "Here, we report the genomic host response in WT mice infected with PA and the essential role of SPHK2 in the ensuing pathogenesis that is relevant to pneumonia and sepsis." (PMID 31842752, 2019). "The fact that both SphK1−/− mice and SphK2−/− mice were characterized by increased survival rate upon sepsis induction made us wonder whether the VEC barrier was influenced by different S1P levels in plasma of the respective mice or not." (PMID 36361636, 2022). "In conclusion, we confirmed patients with severe sepsis have lower serum levels of S1P and report here for the first time that in mice pharmacological (FTY720) and genetic (SPHK2 deficiency) approaches to enhance S1P serum levels reduce the cardiac dysfunction caused by LPS/PepG." (PMID 27277195, 2016). "We therefore suggest that reduced IFN-γ release by SphK1/2 deficient DC dampen the early inflammatory response and cytokine release of macrophages, which, in turn, may have led to the observed increased survival of SphK1−/− and SphK2−/− mice in experimental sepsis." (PMID 36361636, 2022). "Surprisingly, both, SphK1−/− and SphK2−/− mice demonstrated alleviated disease progression compared to wild-type (wt) mice despite their opposite modulation of S1P levels in circulation, suggesting that altered systemic S1P levels have little effect on sepsis outcomes." (PMID 36361636, 2022). "Here, we investigated the role of SphK1 and SphK2 in polymicrobial peritoneal contamination and infection (PCI) as an experimental sepsis model in mice." (PMID 36361636, 2022). "In other inflammatory diseases such as sepsis, plasma or serum S1P levels are known to severely drop in humans, WT mice, and SphK1−/− mice, but not in SphK2−/− mice." (PMID 39062926, 2024). "Studies have shown that SphK1 is 15 times higher than SphK2 in normal human body, while the expression of SphK1 in platelets of sepsis patients is significantly reduced, while SphK2 has no significant change." (PMID 37746079, 2023).
Stroke (5 papers, 2014 to 2021). Sudden impairment of blood flow to a part of the brain due to occlusion or rupture of an artery to the brain. "SPHK2 is under investigation as a target for treating many age-associated conditions, such as cancer, stroke, and neurodegeneration." (PMID 34055895, 2021). "The observed changes in VE-cadherin expression following stroke may be regulated by sphingosine kinase (SphK2), as SphK2-null mice display reduced levels of VE-cadherin and other junctional proteins." (PMID 33424628, 2020). "Additional support for the importance of S1P signaling mechanisms relevant to stroke may come from studies on S1P itself and its biosynthetic enzymes, SPHK1 and SPHK2." (PMID 26576074, 2015). "SphK2, but not SphK1 has been shown to be upregulated by HP and isoflurane in the brain in a HIF-dependent manner and pharmacological inhibition and genetic deletion of SphK2 were shown to abrogate the protective effects of preconditioning in experimental stroke." (PMID 25309325, 2014).
Ureteral obstruction (5 papers, 2018 to 2024). Obstruction of the flow of urine through the ureter. "SphK2−/− has been associated with the attenuation of kidney injury in murine models of cisplatin-induced kidney injury and unilateral ureteral obstruction, but aggravated kidney injury in a murine model of ischemia-reperfusion." (PMID 39062926, 2024). "This presumption is further supported by the fact that SphK2 deletion also protected the mice from kidney fibrosis induced by unilateral ureteral obstruction." (PMID 39062926, 2024). "Renal inflammation in response to unilateral ureteral obstruction showed reduced renal injury in SphK2−/− mice compared to wt mice, which coincided with a relative increase of anti-inflammatory M2 macrophages." (PMID 36361636, 2022). "SPHK2 is required for inflammatory responses in macrophages upon ureteral obstruction and titanium particle stimulation." (PMID 33942347, 2021). "Here we address the in vivo significance of Sphingosine Kinase -2 in renal inflammation/fibrosis in response to unilateral ureteral obstruction using both genetic and pharmacological strategies." (PMID 29518138, 2018). "Permanent unilateral ureteral obstruction was performed on WT and Sphk2-/- mice and both kidneys were harvested at the peak of the early and late inflammatory responses, 3 and 5 days post-surgery." (PMID 29518138, 2018). "Given this information, in the present study we specifically investigated the contribution of Sphk2 to inflammation-induced renal damage resulting from obstructive nephropathy utilizing the Unilateral Ureteral Obstruction (UUO) model from both genetic and pharmacological perspectives." (PMID 29518138, 2018). "In a model of unilateral ureteral obstruction, sphingosine-1-phosphate promotes macrophage glycolysis and inflammation via the sphingosine kinase 2 (Sphk2) pathway, suggesting that sphingolipid signaling may be a critical immunometabolic regulator in kidney injury." (PMID 37234412, 2023).
Arthritis (4 papers, 2018 to 2024). Inflammation of a joint. "Conversely, the genetic deletion of Sphk2 showed minor effects on disease progression in the mouse model of TNF-α-induced arthritis, whereas the pharmacologic inhibition with the SPHK2 inhibitor ABC294640 augmented disease severity." (PMID 32630814, 2020). "However, ABC294640 (SphK2 selective inhibitor) leads to more severe arthritis." (PMID 34737701, 2021). "Confounding these findings is the fact that in arthritis models, genetic deletion of Sphk2 did not recapitulate the beneficial effects achieved by pharmacologic inhibition." (PMID 29518138, 2018).
cholangiocarcinoma (4 papers, 2016 to 2024). A carcinoma that arises from the intrahepatic biliary tree (intrahepatic cholangiocarcinoma) or from the junction, or adjacent to the junction, of the right and left hepatic ducts (hilar cholangiocarcinoma). "Our data provide preliminary insight into the possible use of ABC294640 as an anticancer drug and Sphk2 as a potential therapeutic target for cholangiocarcinoma treatment." (PMID 26956050, 2016). "We found that Sphk2 is overexpressed in five established human cholangiocarcinoma cell lines (WITT, HuCCT1, EGI-1, OZ and HuH28) and a new patient-derived cholangiocarcinoma cell line (LIV27) compared to H69 normal cholangiocytes." (PMID 26956050, 2016). "We aimed to investigate the potential antitumor effect of upamostat and opaganib, individually and in combination, on CCA patient-derived xenografts (PDX) in nude mice using PAX165, a cholangiocarcinoma PDX that expresses substantial levels of SPHK2, PRSS1, PRSS2, and PRSS3." (PMID 38473407, 2024). "We investigated the potential of targeting Sphk2 for the treatment of cholangiocarcinoma." (PMID 26956050, 2016). "Additionally, our results suggest that combinations of Sphk2 inhibition with sorafenib and/or autophagy inhibitors may provide novel and promising strategies to improve the treatment of cholangiocarcinoma." (PMID 26956050, 2016). "Most advanced is the Sphk2 inhibitor ABC294640 (Opaganib, Yeliva®), which has received an orphan drug status for the treatment of cholangiocarcinoma and is presently being tested in a phase 2/3 trial for SARS-CoV-2-induced pneumonia (NCT04467840)." (PMID 34500564, 2021). "In conclusion, we show that inhibition of Sphk2 by a novel highly specific inhibitor ABC294640 inhibits proliferation and induces apoptosis in cholangiocarcinoma cell lines." (PMID 26956050, 2016). "However, the role of Sphk2 and the antitumor activity of its inhibitor ABC294640 are not known in cholangiocarcinoma." (PMID 26956050, 2016).
ischemia (4 papers, 2017 to 2021). A hypoperfusion of the BLOOD through an organ or tissue caused by a PATHOLOGIC CONSTRICTION or obstruction of its BLOOD VESSELS, or an absence of BLOOD CIRCULATION. "In most of these studies, inhibition of S1P signaling in ischemia was achieved by using S1P receptor gene-deficient models or the pharmacological inhibition of SphK1 and SphK2 enzymes, which made I/R injury more severe and/or reduced the benefits of ischemic pre- and post-conditioning." (PMID 32722120, 2020). "The expression of Sphk2 mRNA showed a progressive weak increase that became statistically significant 7 days post-ischemia." (PMID 31165772, 2019). "The reduction of SPHK2 levels may have extremely deleterious effects in the brain, where it is particularly abundant in the microvascular endothelial cells and exerts a protective role against the hypoxic preconditioning-induced ischemia." (PMID 33917593, 2021).
liver fibrosis (4 papers, 2017 to 2022). "Our previous study had reported that S1pr2 and SphK2 played an important role in promoting liver fibrosis." (PMID 33138822, 2020). "However, Sphk2-KO significantly ameliorated immune cell infiltration, hepatocyte ballooning, NAFLD activity score (NAS) and hepatic fibrosis in non-tumorous tissues, which are classic hallmarks of pro-carcinogenic injury in NAFLD-HCC." (PMID 36333295, 2022).
multiple sclerosis (4 papers, 2012 to 2021). A progressive autoimmune disorder affecting the central nervous system resulting in demyelination. "FTY720 (commercially known as fingolimod or Gilenya), upon phosphorylation by SphK2, acts to inhibit S1P receptor signaling, and thereby, potently inflammation and is therefore licensed for treatment of multiple sclerosis." (PMID 34571822, 2021). "FTY720, or fingolimod, an immunomodulatory drug used to treat multiple sclerosis, is phosphorylated by SPHK2, and SPHK2 is a primary enzyme that phosphorylates FTY720 in vivo." (PMID 34055895, 2021). "In multiple sclerosis, FTY720, a pro-drug, acts as an immunosuppressive factor subsequent to its phosphorylation by SPHK2 and modulation of S1PR1." (PMID 34055895, 2021). "The extra sequence at the N-terminal of SphK2 provides for binding of a greater number of substrates such as the immunomodulatory SphK2 drug FTY720, which is now used in the clinic as a therapy for multiple sclerosis, and has already provided a prime example." (PMID 28869494, 2017). "Fingolimod, a recently introduced therapeutic for multiple sclerosis, readily crosses the blood-brain barrier and is phosphorylated to FTY720-phosphate (FTY720-P) predominantly by endogenous sphingosine kinase-2 (SphK-2)." (PMID 22639011, 2012).
Nephropathy (4 papers, 2022 to 2025). A nonspecific term referring to disease or damage of the kidneys. "Therefore, Sphk2 may be a potential new target for the treatment of WT1 mutation-related nephropathy." (PMID 37576146, 2023). "Among them, Daam2, Pdlim2, Asap1, and Sphk2 all of which have a known relationship to kidney diseases." (PMID 39278930, 2024). "Furthermore, there is a report that blocking Sphk2, which is highly expressed in the proximal tubules, improved cisplatin-induced nephropathy, suggesting that Bst1 may be related to other factors besides fibrosis." (PMID 36267620, 2022).
neuroblastoma (4 papers, 2015 to 2021). Neuroblastoma (NB) is the most common solid, extracranial childhood tumor. "Finally, it was reported that both pharmacological inhibition/knockdown of SphK2, and overexpression of S1P lyase/SPP1 in neuroblastoma cells abrogate BACE1-mediated Aβ production whereas exogenous S1P failed to increase amyloid-beta (Aβ) production." (PMID 34135730, 2021).
pancreatic cancer (4 papers, 2016 to 2023). "Here, we show that the inhibition of SphK2 by ABC294640 synergizes with gemcitabine to increase pancreatic cancer cell killing." (PMID 27517489, 2016). "Herein, we show that inhibition of SphK2 by ABC294640 results in an increase in p21 expression that correlates with G1 arrest in three human pancreatic cancer cell lines." (PMID 27517489, 2016). "Here, we show that inhibition of sphingosine kinase-2 by the specific inhibitor ABC294640 is synergistically cytotoxic with gemcitabine toward three human pancreatic cancer cell lines." (PMID 27517489, 2016). "Furthermore, transfection of cells with shRNA downregulating sphingosine kinase 2 increased the effects of FTY-720 on pancreas cancer cell death, which is consistent with a direct effect of FTY-720, but inconsistent with an effect of phosphorylated FTY-720." (PMID 36790532, 2023). "The synergistic killing of pancreatic tumor cells by combined treatment with ABC294640 plus gemcitabine is likely mediated by suppression of RRM2-mediated resistance in parallel with suppression of proliferation by the SphK2 inhibitor." (PMID 27517489, 2016).
pulmonary fibrosis (4 papers, 2020 to 2023). Chronic progressive interstitial lung disorder characterized by the replacement of the lung tissue by connective tissue, leading to progressive dyspnea, respiratory failure, or right heart failure. "In line with the elevation of SphK2, S1P production and pulmonary fibrosis were also significantly increased." (PMID 36226596, 2023). "After CS exposure for six months, histological lung section staining showed disorganized alveolar structure, increased pulmonary fibrosis, and emphysema-like symptoms in wild-type (WT) mice, which were less pronounced in SphK2−/− mice." (PMID 36226596, 2023). "To gain insight into the mechanism underlying SphK2-mediated pulmonary fibrosis under chronic CS exposure, we investigated the CFTR expression in lung tissues from both WT and SphK2−/− mice in response to CS exposure." (PMID 36226596, 2023). "H19 deficiency ameliorated bleomycin-induced pulmonary fibrosis and repressed the activation of TGF-β/Smad and S1pr2/Sphk2 in the lungs of bleomycin-treated mice." (PMID 33138822, 2020). "H19 knockout ameliorated bleomycin-induced pulmonary fibrosis through attenuating the TGF-β/Smad and S1pr2/Sphk2 pathways." (PMID 33138822, 2020). "However, the potential role of SphK2 in regulating the CFTR function and CS-induced pulmonary fibrosis and emphysema remained unclear." (PMID 36226596, 2023). "Our data strongly suggest that functional regulation of CFTR was critically involved in SphK2/S1P signaling-mediated pulmonary fibrosis and inflammation, and CFTR dysfunction has a close link to SphK2/S1P activation-mediated airways remodeling and emphysema after long-term CS exposure." (PMID 36226596, 2023). "We thus propose that H19 contribute to lung fibrosis of IPF may via regulating both TGF-β/smad and S1pr2/SphK2 signalling." (PMID 33138822, 2020). "In preclinical models of pulmonary fibrosis and pulmonary artery hypertension (PAH), genetic deletion of Sphk1 or inhibition of SPHK1 (but not SPHK2) activity with PF543, a small molecule inhibitor of SPHK1, reduced bleomycin-induced development of lung fibrosis or hypoxia-induced PAH in mice." (PMID 35163176, 2022).
pulmonary hypertension (4 papers, 2015 to 2024). Increased pressure within the pulmonary circulation due to lung or heart disorder. "Since then, a functional role for SphK2-dependent histone acetylation has been demonstrated in various conditions, for example, in the pathogenesis of pulmonary hypertension, or in kidney fibrosis." (PMID 39392480, 2024). "S1P levels in serum are increased in patients with pulmonary hypertension, and the expression levels of both SphK1 and SphK2 in remodeled pulmonary arteries are also increased." (PMID 38255229, 2024). "Interestingly, recent research suggests that two important kinases, sphingosine kinase 1 (SphK1) and sphingosine kinase 2 (SphK2), are primary therapeutic targets for pulmonary hypertension." (PMID 26539114, 2015). "SphK1 and S1P levels are markedly augmented in the lungs and pulmonary arterial smooth muscle cells of patients with pulmonary hypertension compared with healthy subjects, whereas SphK2 levels are not." (PMID 38255229, 2024). "It has been proved that SphK1 is involved in the occurrence of pulmonary arterial hypertension (PAH) based on the over-expression of SphK1 in vascular smooth muscle cells (VSMC) and lymphocytes of patients with PAH, and the symptoms of PAH were alleviated in SphK1 knockout mice rather than SphK2." (PMID 34737701, 2021).
Viral infection (4 papers, 2017 to 2024). "In view of the complex functions of SPHK2 in response to virus infection, the role of the SPHK2 protein itself and the S1P-producing kinase activity of SPHK2 in regulation of IAV replication should be evaluated." (PMID 36070294, 2022). "The immunofluorescence analysis showed that SPHK2 proteins still translocated into the nucleus of shHDAC1 A549 cells after viral infection, which suggests that it was the IAV infection that caused SPHK2 to enter into the nucleus." (PMID 36070294, 2022). "Upon IAV infection, some modifications or changes were created in both SPHK2 and TET3, leading to SPHK2’s accumulation in the nucleus and the interaction of SPHK2-HDAC1 complex with TET3, subsequently the specific binding of the IFN-β promoter recruited by TET3 in response to viral infection." (PMID 36070294, 2022).
COVID-19 (3 papers, 2020 to 2021). A disease caused by infection with severe acute respiratory syndrome coronavirus 2. "Opaganib is a novel, orally administered sphingosine kinase-2 (SK2) selective inhibitor developed by RedHill Biopharma for treating COVID-19 patients." (PMID 34356617, 2021). "Indeed, a sphingosine kinase-2 (SphK2) inhibitor, opaganib, which has proved beneficial in the treatment of COVID-19, is currently in global phase 2/3 clinical trials and in US phase 2 studies." (PMID 34353886, 2021). "One of the perceived negative downsides of using SphK2 inhibitors is that SphK2 deletion increases inflammatory cytokine production and macrophage activation, which may contribute to detrimental side effects for COVID-19 patients." (PMID 33003377, 2020).
Glucose intolerance (3 papers, 2020 to 2024). Glucose intolerance (GI) can be defined as dysglycemia that comprises both prediabetes and diabetes. "Hepatocyte-specific ablation of Sphk2 impaired insulin metabolic action and glucose homeostasis, as evidenced by marked glucose intolerance, decreased insulin sensitivity, and hyperinsulinemia." (PMID 32917816, 2020).
Hypertension (3 papers, 2019 to 2024). The presence of chronic increased pressure in the systemic arterial system. "In addition, S1P has been shown to have contractile effects in arteries of a variety of animals, angiotensin II (AngII) treatment leads to hypertension (BP) associated with increased plasma S1P and circulating T cell counts, and SphK2 activity is critical for AngII-induced lymphocyte trafficking." (PMID 37746079, 2023). "3‐(4‐Chlorophenyl)‐adamantane‐1‐carboxylic acid (pyridin‐4‐ylmethyl) amide, named ABC294640, is a selective inhibitor of SPHK2 that can decrease S1P synthesis and rescue Ang II‐induced hypertension in mice." (PMID 38352050, 2024). "Moreover, the dysregulation of SphK2 expression is related to the thrombotic inflammatory phenotype of microvessels and the functional changes of small resistance arteries, leading to the development of hypertension." (PMID 37746079, 2023).